RTN3 (reticulon 3)
Diseases named in the same sentence as RTN3 in open-access papers (continued):
Sharing a sentence is not in itself a finding about the gene and the disease.
myocardial infarction (2 papers, 2024). Gross necrosis of the myocardium, as a result of interruption of the blood supply to the area, as in coronary thrombosis. "Myocardial infarction causes an increase in reticulon 3, which binds to and recruits heat shock protein beta‐1 (HSPB1) into the endoplasmic reticulum, resulting in a decrease in the content of HSPB1 in the cytoplasm." (PMID 38420163, 2024). "In the current study, we found miR-432-5p, a miRNA that protects myocardial infarction via binding with RTN3 to attenuate ADR-induced toxicity." (PMID 39177670, 2024).
nonalcoholic fatty liver disease (2 papers, 2023 to 2024). "Here, we employed public datasets, patients, and several animal models to explore the role of RTN3 in nonalcoholic fatty liver disease (NAFLD)." (PMID 36925557, 2023).
osteoarthritis (2 papers, 2022). A noninflammatory degenerative joint disease occurring chiefly in older persons, characterized by degeneration of the articular cartilage, hypertrophy of bone at the margins and changes in the synovial membrane. "Regarding the biological functions of Rtn3, a study report on osteoarthritis has offered evidence that Rtn3 augments apoptosis and inflammatory response of chondrocytes." (PMID 35317842, 2022).
renal fibrosis (2 papers, 2023 to 2024). A final common manifestation of a wide variety of chronic kidney diseases characterized by glomerulosclerosis and tubulointerstitial fibrosis. "Previously, we detailed the impacts of Rtn3 loss on epithelial cells and ENs in the context of renal fibrosis." (PMID 38937317, 2024). "Such interplay can intensify renal fibrosis, underscoring the multifaceted risks posed by the loss of Rtn3." (PMID 38937317, 2024). "Given prior reports linking Tgfbr2 deletion to enhanced MF recruitment, the Rtn3-null induced loss of the Tgfb2-Tgfbr1/2 axis suggests potential hyper-activation of MFs, resulting in renal fibrosis." (PMID 38937317, 2024). "Additionally, RTN3 deficiency was found to drive the endothelial-to-mesenchymal transition process and disrupt cell-cell communication, further exacerbating renal fibrosis." (PMID 38937317, 2024). "We find loss of Rtn3 in renal tissues could be one of the molecular drivers catalyzing the EndoMT process, further exacerbating renal fibrosis in CKD." (PMID 38937317, 2024). "Our findings highlight Rtn3 as a critical regulator of cellular transitions, particularly in renal epithelial and endothelial cells, and identify Lars2 as a key downstream effector driving mitochondrial dysfunction and renal fibrosis." (PMID 38937317, 2024). "The augmented TNF-α signaling in MCs under Rtn3-null conditions rings alarm bells for potential CKD and renal fibrosis progression." (PMID 38937317, 2024). "Our staining results revealed reduced RTN3 gene expression during the progression of CKD and renal fibrosis, especially in the renal cortex." (PMID 38937317, 2024).
anaemia (1 paper, 2014). "Meanwhile, individuals with the EMR1 rs373533 GT, EMR1 rs461645 CT and RTN3 rs542998 (additive C) genotypes were more susceptible to hyperpyrexia while both females and males with the rs1050828 and rs1050829 SNPs of G6PD, respectively, were more vulnerable to anaemia." (PMID 24934404, 2014).
atherosclerosis (1 paper, 2024). A disease characterized by the build-up of fatty material and calcium deposition in the arterial wall resulting in partial or complete occlusion of the arterial lumen. "A previous study found that RTN3 is involved in the recruitment and differentiation of monocytes in the process of atherosclerosis." (PMID 38420163, 2024).
cardiac arrest (1 paper, 2019). Cessation of breathing and/or cardiac function. "Augmenting RTN3 in the setting of cardiac arrest may be detrimental because intracellular conditions already favor (before hypothermia) the formation of RTN3 aggregates." (PMID 30802174, 2019).
cerebral malaria (1 paper, 2012). A sequestration of Plasmodium falciparum in the brain, which can cause coma and/or seizures. "We observed associations between polymorphisms in reticulon 3 (RTN3- rs542998) and increased risk of cerebral malaria." (PMID 23144702, 2012). "SNPs in the genes encoding IL-13 and reticulon-3 (RTN3) were associated with increased risk of cerebral malaria." (PMID 23144702, 2012).
cystic fibrosis (1 paper, 2024). Autosomal recessive disorder caused by pathogenic variants in the CFTR gene (cystic fibrosis transmembrane conductance regulator), which encodes a chloride and bicarbonate channel expressed in epithelial cells, and follow the diagnosis criteria. "Further, we identified an up-regulation in two EndoMT-related genes in Rtn3-null ENs: Sox17, a developmental transcription factor linked to endothelial-to-fibroblast conversion, and Fxyd5, associated with cystic fibrosis airway epithelia." (PMID 38937317, 2024).
Dengue (1 paper, 2025). "Our scRNA-seq analysis revealed that patient monocytes in the Dengue cohort co-express FCGR3A (CD16) with RTN3." (PMID 41012666, 2025). "Additionally, violin plot analysis demonstrated that RTN3 expression was significantly elevated in intermediate monocytes from Dengue patients compared to healthy controls, with a trend toward higher expression in severe disease." (PMID 41012666, 2025). "Similarly, monocytes from Dengue patients exhibited high RTN3 expression, which correlated with an expansion of intermediate (CD16+) subsets and enriched expression of vesicle trafficking machinery genes." (PMID 41012666, 2025). "To evaluate the RTN3-centered, vesicle-trafficking mechanism during DENV infection, we leveraged a publicly available PBMC scRNA-seq dataset spanning healthy controls, uncomplicated Dengue, Dengue with warning signs (Dengue WS), and severe Dengue." (PMID 41012666, 2025).
diabetes (1 paper, 2021). "Thus, PGRMC1 acts as a size-selective cargo receptor during RTN3-dependent ER-phagy, and is a potential therapeutic target for diabetes." (PMID 34645803, 2021).
enteroviral infection (1 paper, 2024). "Moreover, the 2C of other enteroviruses such as poliovirus and coxsackievirus A16 in the Picornaviridae family is also an interactor of RTN3, implying RTN3 may be a common host factor for enteroviral infection." (PMID 39412487, 2024).
Flavivirus Infections (1 paper, 2024). Infections with viruses of the genus FLAVIVIRUS, family FLAVIVIRIDAE. "This is consistent with the antiviral role of RTN3 in flavivirus infection." (PMID 39412487, 2024).
glioma (1 paper, 2020). A benign or malignant brain and spinal cord tumor that arises from glial cells (astrocytes, oligodendrocytes, ependymal cells). "THBS3, ATP6VOE, and LINC01235 were significantly upregulated while USP32P2, RTN3, and LINC00294 were markedly downregulated in glioma compared to controls." (PMID 32978519, 2020).
glomerulosclerosis (1 paper, 2022). A hardening of the kidney glomerulus caused by scarring of the blood vessels. "HE, picrosirius red and PAS staining indicated that, compared to WT mice, RTN3-null mice presented with overt glomerulosclerosis at 8 months of age and developed hyalinosis at 13 months." (PMID 35596061, 2022). "HE and Masson staining revealed that RTN3-null mice developed more severe glomerulosclerosis and kidney fibrosis than WT mice, and the levels of CR were also higher in RTN3-null mice than in WT mice." (PMID 35596061, 2022). "In this study, by employing hematoxylin and eosin (HE) staining, periodic acid-Schiff (PAS) staining, picrosirius red staining, and Masson staining, we noted kidney fibrosis, including glomerulosclerosis and tubulointerstitial fibrosis, in RTN3-knockout (RTN3-null) mice at 13 months of age." (PMID 35596061, 2022). "Glomerulosclerosis and kidney fibrosis showed age-dependent progression in RTN3-null mice." (PMID 35596061, 2022).
Hydrocephalus (1 paper, 2026). Hydrocephalus is an active distension of the ventricular system of the brain resulting from inadequate passage of CSF from its point of production within the cerebral ventricles to its point of absorption into the systemic circulation. "It followed that in hydrocephalus post IVH, the expression change of the RTN3/AMPK/ERS pathway may be a new molecular mechanism concomitant with neurofunctional recovery." (PMID 41578884, 2026).
hyperlipidemia (1 paper, 2025). "Additionally, reticulon 3 (RTN3) regulates triglyceride biosynthesis and storage through its interaction with heat shock protein family A (HSP70) member 5, which may be a mechanism for hyperlipidemia occurrence." (PMID 40245021, 2025).
Hypertension (1 paper, 2024). The presence of chronic increased pressure in the systemic arterial system. "We first linked RTN3 with blood pressure regulation in humans and mice and reported the first RTN3 variant in a hypertension patient." (PMID 38352050, 2024). "We reported the first RTN3 variant (c.116C>T, p.T39M) identified in a hypertension patient to further confirm this correlation." (PMID 38352050, 2024). "Overall, our data preliminarily elucidated the importance of RTN3 in blood pressure regulation and emphasized the causative role of S1P signal dysregulation in endothelium dysfunction and hypertension." (PMID 38352050, 2024). "We also identified an RTN3 variant (c.116C>T, p.T39M) in a family with hypertension." (PMID 38352050, 2024). "This variant was detected to reduce ceramide and S1P in HUVECs and may be the first RTN3 variant reported in hypertension." (PMID 38352050, 2024). "We speculated that the RTN3 variant inhibited protein degradation and that RTN3 accumulation disrupted the balance of sphingolipid metabolism, triggering hypertension." (PMID 38352050, 2024). "Given that hypertension is not a disease with onset at an early age, we considered it natural that the young RTN3‐variant carrier was unaffected." (PMID 38352050, 2024). "High RTN3 expression was accompanied by hypertension, and the absence of RTN3 resulted in hypotension in mice." (PMID 38352050, 2024). "Considering the effects of RTN3 on autophagy, we further confirmed that increased RTN3 promoted CERS2 selective autophagy and then reduced the levels of ceramide and S1P in HUVECs, which may disrupt endothelial barrier function and ultimately induce hypertension." (PMID 38352050, 2024).
hypotension (1 paper, 2024). "We reported that increased RTN3 was found in patients and that RTN3‐null mice presented hypotension." (PMID 38352050, 2024).
interstitial lung disease (1 paper, 2025). A diverse group of lung diseases that affect the lung parenchyma. "In short, we identified two mutations (c.548A > G/p.E183G) of RTN3 in patients with interstitial lung diseases." (PMID 39972424, 2025).
liver diseases (1 paper, 2023). "Because no previous study focused on RTN3 and liver diseases, we first analyzed the RNA levels of RTN3 in public datasets (GSE185051, GSE200409, and GSE200482)." (PMID 36925557, 2023).
nonalcoholic steatohepatitis (1 paper, 2023). "Our study indicated that RTN3 was important in NAFLD and lipid catabolism and that an increase in RTN3 in the liver might be a risk factor for nonalcoholic steatohepatitis and NAFLD." (PMID 36925557, 2023).
Onset (1 paper, 2021). The age group in which disease manifestations appear. "In patients with sporadic early-onset AD and sporadic late-onset AD, multiple RTN-3 variants, mainly in the 5′ non-coding region and the N-terminal domain of RTN-3, were found." (PMID 33924890, 2021).
Senile plaques (1 paper, 2017). Senile plaques are extracellular deposits of amyloid in the gray matter of the brain. "Together, our data show that RTN1 and RTN3 have differential effects on the formation of senile plaques in Alzheimer’s brains and that RTN3 has a more prominent role in Alzheimer’s pathogenesis." (PMID 28733667, 2017).
steatosis (1 paper, 2023). Increased lipid within the cytoplasm of cells. "The results showed that the RNA levels of RTN3 were increased dramatically in the NAFLD patient group, HFD mouse group, and steatosis‐steatohepatitis diet (SSD) mouse group compared to healthy controls." (PMID 36925557, 2023).
thyroid cancer (1 paper, 2026). "This study found that RTN3 is low-expressed in thyroid cancer, and is related to poor prognosis and insensitivity to MEK inhibitors." (PMID 41813657, 2026). "As ER is the primary site of cholesterol synthesis, we aimed to study how RTN3 regulates cholesterol concentration and influences tumor progression and sensitivity to MEK inhibitors in thyroid cancer." (PMID 41813657, 2026). "Downregulation of RTN3 lead to stabilization of DHCR7 and elevate cholesterol concentration, activating EGFR/ERK pathway and contributes to progression of thyroid cancer, which can be rescued by HMG-CoA reductase inhibitor Simvastatin." (PMID 41813657, 2026).
tumor (11 papers, 2010 to 2026). "For example, certain studies have reported significant upregulation of the levels of RTN3 mRNA and proteins in tumor tissues as a risk factor in risk models." (PMID 37575244, 2023). "We identified RTN3 as a tumor suppressor and a biomarker of sensitivity to MEK inhibitors and verified the role of cholesterol in drug resistance." (PMID 41813657, 2026). "Endoplasmic reticulum (ER) proteins modulate cell biosynthesis and mediate tumor progression, among which Reticulon 3 (RTN3) is verified to play important roles in cancers." (PMID 41813657, 2026). "RTN3 exerts pleiotropic roles in amyloid deposition, tumor invasion, and lipid accumulation by interacting with various proteins to alter their enzyme activity, subcellular localization, and protein complex stability." (PMID 38420163, 2024). "RTN3 mRNA expression was elevated in tumour tissues from the TCGA-STAD and GES13911 datasets, whereas the fold change was relatively low." (PMID 35428758, 2022). "UPB1 and SOCS2 exhibited lower expression than the corresponding normal tissues, while RTN3 showed a tendency of increase expression in tumor tissues (p = 0.09)." (PMID 28717245, 2017). "The results demonstrated that UPB1 and SOCS2 were downregulated in HCC tissues (UPB1: p < 0.0001; SOCS2: p < 0.0001), while the expression of RTN3 was increased in tumor tissues (p < 0.0001)." (PMID 28717245, 2017). "The results of this study indicate that the knockdown of RTN3 effectively inhibits the proliferation, invasion, and metastasis of tumor cells, thereby confirming the importance of the genes identified in the risk model and providing initial insights into the role of RTN3 in HCC." (PMID 37575244, 2023). "Furthermore, RTN3 was one of the top three upregulated genes in chemotherapy-sensitive epithelial ovarian cancer samples pointing toward an anti-tumor role under these conditions." (PMID 30250843, 2018). "The possibility that Praf2, forming a complex with RTN proteins could be able to potentiate the anti-apoptotic activity of Bcl-2/xL, as shown for RTN3, could also help to explain why an increased Praf2 expression would be selected during tumor formation." (PMID 21203533, 2010). "However, we succeeded in developing a three-gene signature including UPB1, SOCS2 and RTN3 based on gene-expression profiles of tumor tissue in this study, and fortunately we have validated this model with two independent GEO microarray datasets produced from different platforms." (PMID 28717245, 2017). "This secretion triggers a miR-4488/RTN3/FABP5/MMP2 feedback loop in pNEN cells, highlighting a complex interplay between pNEN cells and the tumor microenvironment that promotes tumor progression and metastasis." (PMID 38904015, 2024). "RTN3 is positively correlated with HCC and its levels were significantly increased in tumor tissues compared to healthy ones." (PMID 30250843, 2018). "The expression of UPB1 was found to be correlated with tumor capsule invaded, and no other significant association was observed between UPB1, SOCS2 and RTN3 expression and clinicopathological variables perhaps partly because of the relatively small sample size." (PMID 28717245, 2017). "To ensure that miR-4488, RTN3, and FABP5 do not independently affect the expression of MMP2 in tumor cells, we conducted Western blot experiments." (PMID 38904015, 2024). "RTN3 was upregulated in HCC tumor tissue compared to nontumor tissue (p = 0.00001), while expression of UPB1 in tumor tissue was significantly lower than that in nontumor tissue (p < 0.00001)." (PMID 28717245, 2017).
neurodegenerative disease (8 papers, 2012 to 2025). A disorder of the central nervous system characterized by gradual and progressive loss of neural tissue and neurologic function. "Among them, the top-ranked gene RTN3 (Reticulon 3) has been shown to be involved in the development of neurodegenerative diseases, especially in AD (according to the GeneCards database)." (PMID 35892682, 2022). "Reticulon 3 (RTN3) is an endoplasmic reticulum protein that has previously been shown to play roles in neurodegenerative diseases, but little is known about its function in the kidneys." (PMID 35596061, 2022). "Our data thus far predict that activation of TrkB alone, in the absence of cooling should induce the cold-shock proteins, RBM3 and RTN3, and confer neuroprotection in the context of neurodegenerative disease." (PMID 33563652, 2021). "Aggregates of RTN3 have been reported in the brain of AD patients and other neurodegenerative diseases." (PMID 31141529, 2019). "We propose that the control of RTN3 expression through escape from inhibition of translation on cooling at the levels of initiation and elongation provides new targets for neuroprotective therapies in neurodegenerative disease." (PMID 28238655, 2017). "Finally, we show that RTN3 expression, downstream of RBM3 induction, mediates cooling-induced neuroprotection in mice with neurodegenerative disease and importantly is neuroprotective even in the absence of cooling." (PMID 28238655, 2017).
cancer (6 papers, 2018 to 2026). A tumor composed of atypical neoplastic, often pleomorphic cells that invade other tissues. "Despite the fact that information relative to its role in cancer is still limited, it was first shown that RTN3 overexpression triggers tumor necrosis factor-related apoptosis-inducing ligand (TRAIL)-, tumor necrosis factor (TNF)-α and Fas-dependent apoptosis." (PMID 30250843, 2018). "However, the precise role of RTN3 in cancer needs to be further elucidated." (PMID 35992272, 2022).